GSK3B (glycogen synthase kinase 3 beta)
Diseases named in the same sentence as GSK3B in open-access papers (continued):
Sharing a sentence is not in itself a finding about the gene and the disease.
Sepsis (continued). "In the LPS-induced sepsis model, GSK-3β phosphorylation at Ser9 was found to be initially reduced but recovered to baseline level after a short period of time." (PMID 23533310, 2013). "We aim to further explore whether miR-29b-3p/GSK-3β could serve as a predictor of sepsis progression or a therapeutic target for sepsis." (PMID 39502342, 2024). "It was suggested that LGS may inactivate GSK-3β by phosphorylation of Ser9, reduce LPS-induced leukocytes migration in sepsis." (PMID 37456759, 2023). "Furthermore, the mechanism by which NAD+/SIRT1 alleviates the sepsis‐induced AKI involves the regulation of glycogen synthase kinase‐3β (GSK‐3β) / nuclear factor erythroid 2‐related factor 2 (Nrf2) signalling pathway." (PMID 35137552, 2022). "The study, therefore, sheds light on the mechanisms underlying the renoprotective capacity of NAD+ and identifies NAD+/SIRT1/GSK‐3β/Nrf2 pathway as a potential therapeutic target, which might be used to prevent or ameliorate sepsis‐induced AKI." (PMID 35137552, 2022). "However, it is the first report documentingthe activation of GSK-3β in sepsis-induced inflammation and heart injury." (PMID 33605309, 2021). "Accordingly, it has been hypothesizedthat oleuropein-mediated potential useful effects in sepsis-induced myocardialinjury may be possibly mediated through modulation of GSK-3β and NF-kB." (PMID 33605309, 2021). "Our study demonstrated that MitoQ could protect sepsis-induced acute lung injury by activating the PI3K/Akt/GSK-3β/mTOR pathway in rats." (PMID 31815144, 2019). "To prove our hypothesis that FOXO3A might be one of the targets of GSK‐3β in sepsis‐induced cardiac dysfunction, we used CHIR‐99021 and LiCl to inhibit GSK‐3β." (PMID 31503410, 2019). "In our study, we investigated whether MitoQ could play a role in sepsis-induced ALI through the PI3K/Akt/GSK-3β/mTOR signaling pathway and found that the PI3K/Akt/GSK-3β/mTOR pathway could be activated by MitoQ treatment." (PMID 31815144, 2019). "MitoQ could protect sepsis-induced acute lung injury through the activation of the PI3K/Akt/GSK-3β/mTOR pathway in rats." (PMID 31815144, 2019). "Previous studies have indicated that GSK‐3β is involved in the modulation of sepsis." (PMID 31503410, 2019). "GSK-3β was found to strongly promote the production of proinflammatory cytokines by TLR-induced MyD88-dependent and MyD88-independent pathways, and the inhibition of GSK-3β was shown to protect the host from several inflammatory diseases such as colitis, arthritis, and sepsis-induced organ failure." (PMID 29849928, 2018). "This study also provides a clear basis for the use of a novel anti-platelet agent, exogenous CO, as an effective strategy for improving platelet function and support, a model in which the glycoprotein-mediated PI3K-Akt-GSK-3β pathway effectively regulates platelet activation during sepsis." (PMID 27020460, 2016). "Therefore, we aimed to investigate the protective effects of GSK-3β inhibition on polymicrobial sepsis-induced liver injury by a mouse cecal ligation and puncture (CLP) model and to further explore the possible mechanisms." (PMID 25525303, 2014). "Although the role of GSK-3β in endotoxin shock and live bacterial infection has been extensively investigated, less information is available on the possible effects of GSK-3β inhibition in polymicrobial sepsis, which is more representative of the clinical condition." (PMID 25525303, 2014). "GSK-3β inhibition has been successfully tested as a protective strategy in sepsis." (PMID 25525303, 2014). "However, the role of GSK-3β inhibition in the pathogenesis of live injury induced by polymicrobial sepsis and its regulatory mechanisms remain poorly understood." (PMID 25525303, 2014). "In summary, we documented that GSK-3β inhibition could improve the survival of mice with polymicrobial sepsis, ameliorated liver injury, and reduced hepatic apoptosis." (PMID 25525303, 2014).
Sepsis (continued). "Since GSK-3β inhibition can provide anti-inflammatory effects in vitro and in vivo, it could offset cytokine storm-related tissue injury during sepsis and might therefore act as an alternative therapeutic strategy beyond antibiotic treatment." (PMID 23533310, 2013). "However, the protective effect of GSK-3β inhibition was mostly demonstrated in LPS-induced sepsis models and only a few studies explored the possible effect of GSK-3β inhibition against live bacteria, which is more similar to clinical conditions." (PMID 23533310, 2013). "Thus, a future goal may be to tailor therapies to target the GSK3β-mediated pathways that contribute to uncontrolled inflammation, and accelerate organ dysfunction and failure in patients with sepsis." (PMID 33203111, 2020). "CaMKIV signaling mediated the autophagic response to sepsis-induced AKI, by inhibiting GSK3β and FBXW7 expression and maintaining mTOR." (PMID 37215112, 2023). "In the late phase of sepsis, we suggest targeting neuroinflammation, BBB dysfunction, Aβ and tau protein phosphorylation, glycogen synthase kinase-3 beta (GSK3β), and the receptor for advanced glycation end products (RAGE)." (PMID 35488237, 2022). "The downstream GSK3B gene was significantly downregulated in Native Hawaiians CRC-S patients and this gene plays a role in sepsis onset and progression." (PMID 36450776, 2022). "The observed downregulation of the GSK3B gene and its effects on numerous pathways highlighted in our IPA analyses point to its role as a potential gate keeper of sepsis progression." (PMID 36450776, 2022). "Moreover, transcriptional differences between Native Hawaiians and Japanese CRC-S patients suggest early and late responses are significantly altered in sepsis progression, which may be reflected in the potential biomarkers we identified such as GSK3B, WFDC2 and MTRNR2L1." (PMID 36450776, 2022). "Based on these studies, we ventured to investigate the mechanism of action of GSK-3β and NF-κB with CREB signaling pathways in sepsis-induced ALI." (PMID 33995024, 2021). "We investigated the role of GSK-3β in the regulation of NF-κB and CREB signaling pathways during sepsis-induced ALI." (PMID 33995024, 2021). "FOXO3A was identified to be positively regulated by GSK‐3β through degrading β‐catenin, and the knock‐down of FOXO3A in cardiomyocytes with siRNAs further confirmed its positive role on sepsis‐induced cardiomyocytes dysfunction." (PMID 31503410, 2019). "Polymicrobial sepsis was induced by cecal ligation and puncture (CLP), and SB216763 was used to inhibit GSK-3β in C57BL/6 mice." (PMID 25525303, 2014). "Inhibition of myocardial GSK3β positively correlated with maintenance of cardiovascular function and improved survival outcome in CLP sepsis." (PMID 23028587, 2012). "Cyasterone defends against sepsis-induced ALI by inhibiting inflammatory responses and oxidative stress, which depends heavily on the upregulation of the Nrf2 pathway through phosphorylation of AKT(Ser473)/GSK3β(Ser9)." (PMID 37853474, 2023). "GSK-3β gene expression data was extracted and analyzed with clinical grouping information, and the results suggested that GSK-3β expression was significantly upregulated in the sepsis group, with statistically significant differences (p < 0.001)." (PMID 37456759, 2023). "The results shown that the effect of GSK‐3β inhibition on sepsis was prevented by the knock‐down of β‐catenin, indicating that β‐catenin exerts an important role in GSK‐3β related sepsis." (PMID 31503410, 2019). "Thus, inhibition of GSK-3β could reduce the level of TNF-α and increase survival in the GAS-induced sepsis model." (PMID 23533310, 2013). "Interestingly, we did not see any significant difference in myocardial GSK3β phosphorylation in p110α transgenic mice in the presence or absence of sepsis." (PMID 23028587, 2012).
dementia (31 papers, 2011 to 2025). Loss of intellectual abilities interfering with an individual's social and occupational functions. "The large increase in basal fasted phosphorylation of GSK3β could also have important implications for dementia research since GSK3 overactivity is implicated in the pathogenesis of tau." (PMID 37531359, 2023). "GSK3β is strongly implicated in dementia and ALS and so GSK3β inhibitors may prove to be therapeutic for FTD/ALS." (PMID 35693938, 2022). "GSK-3β genes have been identified as potential candidate susceptibility genes for dementia." (PMID 24319473, 2013). "A study conducted on elderly subjects observed an increase in GSK‐3β activity in patients with AD presenting depressive symptoms or in those exhibiting mild dementia." (PMID 40757845, 2025). "All of which increase the deposition of β-amyloid, tau proteins, and GSK3β, leading to an earlier onset of dementia." (PMID 36151524, 2022). "The serine-threonine protein kinase B (AKT1/2) and GSK3-β are involved in the brain insulin/insulin-like growth-factor-1 (IGF-1) signaling whose dysregulation correlates with the severity of dementia symptoms in sAD." (PMID 34830036, 2021). "For instance, in AD and other dementias, inactivation of GSK3β together with activation of stress kinases ERK1/2 or JNK, play a key role in pTau aggregation pattern." (PMID 33319314, 2021). "Among them are 7 commonly studied learning and memory genes (PubMed citations>20) that have at least 1.5-fold decrease of Pol II signals at both TSS and exons in Top3β-KO mice under FC, including those important for AD (App, Mapt, Gsk3b) and dementia (Fus)." (PMID 32561719, 2020). "Moreover, elevated GSK‐3β activity in the peripheral blood of patients with AD has been demonstrated to be positively correlated with the severity of dementia." (PMID 40757845, 2025). "Moreover, high activity of GSK3β in the peripheral blood of AD patients has been found to be positively correlated with the severity of dementia." (PMID 38946682, 2024). "Since IGF and GSK-3β are also perturbed in the brain of Guam and Japanese ALS/PDC patients, and insulin resistance is an established risk factor for dementia, the cycad genotoxins might induce tau pathology in GD and PDC by inducing brain insulin resistance." (PMID 22073019, 2011). "Platelet GSK-3β activity could be a useful biomarker to predict cognitive decline, suggesting the feasibility of identifying vulnerable population and implementing early prevention for dementia." (PMID 38660514, 2024). "Mechanistically, it has been proposed that during AD and related dementias, GSK3β activity may become deregulated due to its increased expression or as a result of alterations in upstream regulators of GSK3β, leading to enhancement of NMDAr-LTD and neurodegeneration." (PMID 32952546, 2020). "Methamphetamine abuse often leads to dementia, and experimental evidence has shown that methamphetamine contributes to tau hyperphosphorylation through the AKT/GSK3β signaling pathway." (PMID 38946682, 2024). "GSK-3β is an essential kinase in the insulin pathway that serves as a vital link between the pathologies of T2DM and dementia." (PMID 38660514, 2024). "It is known that while LTP (long-term potentiation) promotes memory and is mediated by the GSK-3β pathway, LTD contributes to the generation and progression of dementia." (PMID 35453527, 2022). "Therefore, an established model incorporating aging, ApoE ε4 genotype, olfactory decline, an increased plasma Aβ1-42/Aβ1-40, and an increased platelet GSK-3β activity has a great potential for predicting who may develop dementia (including AD) in T2DM patients." (PMID 34746146, 2021). "Several of the connections we found in our network analysis, such as GSK3B, MAPT, ADAM17, and PSEN1 are also involved in other dementias than AD." (PMID 31797941, 2019).
dementia (continued). "Several preclinical and clinical data strongly link GSK-3β to dementia: different inhibitors of GSK3B activity block neurodegeneration in vitro, and GSK-3β -mediated Wnt signaling can mediate amyloid peptide toxicity in vitro." (PMID 24908109, 2014). "The tau pathology in the STZ rodent model of dementia is preceded by early changes in the phosphatidylinositol-3-kinase (i.e., PI3K, phospho-Akt, GSK-3β) insulin/IGF-signaling pathway." (PMID 22073019, 2011). "Therefore, VIP maintained the intrinsic inhibitory activity of GSK3β and BACE1 and exerted a synergistic anti-dementia therapeutic effect, which was consistent with the improvement in behavioral tests observed in APP/PS1 mice treated with VIP@siScr." (PMID 38734698, 2024). "Therefore, a prediabetic state that impairs insulin-mediated inhibition of GSK3β by reduced expression of GSK3β-pSer9 may allow pathological activation of GSK3β and tau hyperphosphorylation and contribute to the increased incidence of dementia in people with prediabetes." (PMID 38416718, 2024).
cognitive decline (30 papers, 2016 to 2026). "Tau phosphorylation and oAβ deposition have been associated with rapid cognitive decline, and the Akt/ GSK-3β (Ser9) signaling axis acts as an upstream regulator." (PMID 39574138, 2024). "Our previous study has found that aging, increased activity of GSK-3β, the presence of ApoE ε4 genotype, and olfactory dysfunction are associated with cognitive decline in T2DM patients." (PMID 38660514, 2024). "Our results indicated that age (OR 1.09, 95% CI 1.04, 1.14), ApoE4 genotype (OR 2.68, 95% CI 1.11, 6.47), platelet GSK-3β activity (OR 1.87, 95% CI 1.05, 3.34) are independently associated with cognitive decline at follow-up." (PMID 38660514, 2024). "In summary, our data demonstrate that STP dysregulation of Akt/GSK-3β pathway is associated with apoptosis, tau hyperphosphorylation, Aβ overproduction, synaptic dysfunction and cognitive decline." (PMID 38095632, 2023). "According to these data, topiramate’s ability to suppress hippocampal apoptotic cell death and inactivate the pro-apoptotic GSK-3β is, at least partly, engaged in rescuing the cognitive decline associated with cadmium intoxication." (PMID 37765022, 2023). "Further analysis showed that the presence of the ApoEε4 allele in T2DM patients may interact with increased GSK-3β activity to accelerate cognitive decline." (PMID 38660514, 2024). "The implicated mechanisms that mediated the cognitive decline in animals were investigated by measuring the neurotoxic signals, such as phosphorylated tau (p-tau) and its upstream effector glycogen synthase kinase-3 beta GSK-3β." (PMID 38002000, 2023). "Overexpression of GSK3β was also associated with cognitive decline in another behavioral test." (PMID 31429527, 2019). "In agreement with the present results, the activity of GSK3β was found to increase prior to the formation of nurofibrillary tangles in the brains of AD patients, and the overexpression of this kinase was also found in the prefrontal cortex and was associated with cognitive decline in AD patients." (PMID 39167347, 2024). "The GSK‐3β inhibitor 9‐ING‐41 showed promise as a potential therapeutic for T2DM‐related cognitive decline." (PMID 40905109, 2025). "Tau hyperphosphorylation, mediated by glycogen synthase kinase-3β (GSK-3β), is a key driver of progressive cognitive decline in AD." (PMID 40626308, 2025). "ApoE4 exacerbates Alzheimer's‐like pathologies in T2DM by activating GSK‐3β and disrupting insulin signaling, leading to tau hyperphosphorylation, neuroinflammation, and cognitive decline." (PMID 40905109, 2025). "We have previously observed that cognitive decline in patients with T2DM is associated with advanced age, impaired olfactory function, increased platelet GSK-3β activity, and ApoE4 genotype." (PMID 38660514, 2024). "We have previously reported that an increasing aging, the increased olfactory score, the increased platelet GSK-3β activity, and the ApoE ε4 genotype were correlated with the cognitive decline in T2DM patients." (PMID 34746146, 2021). "By inhibiting the activation of GSK3β through Ser-9 phosphorylation, exercise could thus contribute to the prevention of cognitive decline in T2DM." (PMID 40274715, 2025). "However, the precise mechanisms by which ApoE ε4 influences GSK‐3β activity and exacerbates brain pathology and cognitive decline in T2DM patients remain poorly understood." (PMID 40905109, 2025). "It is known that IR may inhibit the neuronal PI3-K/AKT pathway and enhance GSK3-β activation to increase tau protein hyperphosphorylation, a pathological indicator of cognitive decline, such as delirium." (PMID 39054513, 2024). "IR could potentially increase tau hyperphosphorylation by inhibiting PI3-K/AKT and enhancing GSK3-β activation, while an imbalance in tau protein phosphorylation is a pathological indicator of cognitive decline." (PMID 37904099, 2023). "We wonder whether the cognitive decline in ApoE ε4‐carried T2DM patients is mediated by the upregulation of GSK‐3β activity." (PMID 37700547, 2023).
cognitive decline (continued). "Meanwhile, GSK-3β inhibition could improve cognitive decline by inducing M2 polarization of microglia, indicating that this protein is a potentially important target for the treatment of postoperative cognitive dysfunction in elderly patients." (PMID 33354162, 2020). "In addition, GSK3β may represent a potential biomarker of incipient cognitive decline in patients with PDD." (PMID 34707492, 2021). "We found that EA therapy was beneficial in improving cognitive decline by promoting glucose uptake in the hippocampus and that the underlying molecular mechanisms might be associated with phosphorylation of Tau protein through the AKT/GSK3β signaling pathway." (PMID 33328854, 2020). "Specifically, we demonstrated that hDPSCs significantly improved cognitive decline and intracranial microenvironment in AD mice and that the beneficial effects were largely dependent on AKT/GSK3β-mediated Nrf2 activation and nuclear accumulation." (PMID 38740746, 2024). "It was reported that modulation of the phosphoinositide 3-kinase (PI3K)/protein kinase B(Akt)/glycogen synthase kinase-3β(GSK-3β) pathway retards ICV-STZ-induced neuro-inflammation, tau hyperphosphorylation, and cognitive decline." (PMID 34943213, 2021). "Our data reveal that α7-nAChR attenuates cognitive decline and neuroinflammation and oxidative stress through PI3/AKT/GSK-3β pathway." (PMID 31736967, 2019). "Activation of H3Rs mediates a series of intracellular signaling pathways that are involved in the pathogenesis of AD, including the Gαi/o-protein-coupled inhibition of AC, downstream exaggeration of cognitive decline through transduction of cAMP/CREB, and activation of PI3K/AKT/GSK3β signaling." (PMID 31024245, 2019).